SNAPC3 (small nuclear RNA activating complex polypeptide 3)
Description:
Part of the SNAPc complex required for the transcription of both RNA polymerase II and III small-nuclear RNA genes. Binds to the proximal sequence element (PSE), a non-TATA-box basal promoter element common to these 2 types of genes. Recruits TBP and BRF2 to the U6 snRNA TATA box.
Synonyms: SNAP50; PTFbeta; MGC33124; MGC132011
Tractability: Small molecule: a structure with a bound ligand is known. PROTAC: ubiquitination databases record sites on it.
Gene: Protein-coding gene on chromosome 9 (15,422,734 to 15,465,953, forward strand). Ensembl gene ENSG00000164975.
Subcellular location: Nucleus
Subcellular location (Human Protein Atlas): Nuclear bodies; Nucleoplasm; Nucleoli
Pathways (Reactome):
Gene expression (Transcription): RNA Polymerase III Abortive And Retractive Initiation; RNA Polymerase III Transcription Initiation From Type 3 Promoter; RNA polymerase II transcribes snRNA genes
Gene Ontology:
Molecular function: protein binding; bent DNA binding; core promoter sequence-specific DNA binding; DNA binding; RNA polymerase II cis-regulatory region sequence-specific DNA binding; RNA polymerase III general transcription initiation factor activity; RNA polymerase III type 3 promoter sequence-specific DNA binding
Biological process: snRNA transcription; snRNA transcription by RNA polymerase II; snRNA transcription by RNA polymerase III; transcription by RNA polymerase II; transcription by RNA polymerase III
Cellular component: nucleoplasm; snRNA-activating protein complex; nucleus
Genetic constraint (gnomAD): Loss-of-function variants: 21 observed, 14.87 expected, observed/expected ratio (o/e) 1.41, 90% interval 0.99 to 1.88. The synonymous counts are far from expectation, so gnomAD's model fits this gene poorly and the ratio says little. Missense variants: 369 observed, 246.52 expected, observed/expected ratio (o/e) 1.5, 90% interval 1.37 to 1.63. Synonymous variants: 135 observed, 102.4 expected, observed/expected ratio (o/e) 1.32, 90% interval 1.14 to 1.52.
Homologues: Orthologues: chimpanzee SNAPC3 (100% identical), macaque SNAPC3 (98% identical), pig SNAPC3 (91% identical), rabbit SNAPC3 (90% identical), guinea pig SNAPC3 (88% identical), rat Snapc3 (85% identical), mouse Snapc3 (84% identical), tropical clawed frog snapc3 (63% identical), zebrafish snapc3 (48% identical), Caenorhabditis elegans snpc-3.4 (23% identical), Drosophila melanogaster Pbp49 (23% identical), Caenorhabditis elegans snpc-3.1 (21% identical), and 2 more.
Diseases named in the same sentence as SNAPC3 in open-access papers:
SNAPC3 is named in the same sentence as 4 diseases in open-access papers, as found by Europe PMC text mining. Sharing a sentence is not in itself a finding about the gene and the disease. The quoted sentences say what the papers report.
osteosarcoma (2 papers, 2021 to 2024). A usually aggressive malignant bone-forming mesenchymal neoplasm, predominantly affecting adolescents and young adults. "Again, we identified nine genes related to differences in immune cell infiltration in osteosarcoma, four of which are SORBS2, BAIAP2L2, SNAPC3 and ZDHHC21 with low abundances and they have higher disease-free survival probability than the group with high abundances." (PMID 34922489, 2021).
Obesity (1 paper, 2025). Accumulation of substantial excess body fat. "While support for other genes identified herein is limited in the literature, SNAPC3, which validated in CCHC, and TMEM245, which generalized to liver tissue, have connections to obesity-related traits." (PMID 41006818, 2025).
schizophrenia (1 paper, 2025). A major psychotic disorder characterized by abnormalities in the perception or expression of reality. "Lastly, SNAPC3, a component of the small nuclear RNA transcription complex, is associated with schizophrenia and early-life growth trajectories via epigenetic regulation." (PMID 41006818, 2025).
tumor (1 paper, 2011). "Additionally, a T2/OncZ transposon insertion in Snapc3 was observed in tumor 8T, a gene previously identified with a T2/Onc insertion in mouse tumor samples." (PMID 21533036, 2011).